RARG (retinoic acid receptor gamma)
Diseases named in the same sentence as RARG in open-access papers (continued):
Sharing a sentence is not in itself a finding about the gene and the disease.
prostate carcinoma (continued). "The pan-RAR antagonist AGN194310 was more effective against patients’ prostate cancer cells and cell line cells than normal prostate fibroblasts and epithelial cells, and the RARγ antagonist AGN205728 was more effective against prostate cancer cell line cells than the normal prostate RWPE-1 cells." (PMID 40362593, 2025). "A combination of docetaxel and a low dose of AGN205728 (10−7 M) showed a substantial reduction in prostate cancer cell viability, revealing that RARγ antagonists combined with chemotherapy may be effective in treating prostate cancer." (PMID 38928275, 2024). "In the retinoic acid receptor family, the overexpression of RARβ has been found to reduce the proliferation of prostate cancer cells, and RARγ may inhibit the development of prostate cancer by competitively binding AR binding sites." (PMID 39771106, 2024). "Hence, RARγ is expressed by most of the prostate cancer cells, suggesting that expression is deregulated within prostate cancer cells." (PMID 36768694, 2023). "Targeting RARγ to treat disease is a promising prospect because for prostate cancer, agonism of RARγ stimulated the growth of and colony formation by prostate cancer cell line cells and antagonising led to necroptosis of the cell line colony forming CSC-like cells and patients’ cells." (PMID 37082619, 2023). "As tested for prostate cancer, antagonizing RARγ was sufficient to drive necroptosis." (PMID 35563205, 2022). "Prostate cancer cells depend on active RARγ for their survival." (PMID 35563205, 2022). "That gene expression regulated by RARγ or RARβ might be more necessary to the growth of prostate carcinoma cells than their normal counterparts remains an interesting possibility." (PMID 15266311, 2004). "From these findings, the roles of RARγ and FOXA1 in prostate cancer deserve close attention by means of orthotopic transplantation of normal and tumour organoids." (PMID 40362593, 2025). "Low concentrations of ATRA (10−11–10−9 M), sufficient to activate RARγ, stimulated the proliferation of the prostate cancer cell lines LNCaP, DU145, and PC-3, and the RARγ agonist AGN205327 exerted the same effect." (PMID 38928275, 2024). "The normal prostate epithelium was less sensitive to the RARγ antagonist and pan-RAR antagonist than prostate cancer cells, and fibroblasts and blood mononuclear cells were insensitive." (PMID 35563205, 2022). "A gene network, comprising of numerous RARγ target genes, such as SOX15, has been found to be correlated with poor disease-free survival of prostate cancer patients." (PMID 34831421, 2021). "In contrast, the expression levels of several NRs including LXRα, LXRβ, RARγ, and RXRα are downregulated in malignant-transformed prostate epithelial RWPE-2 cells as well as clinical prostate cancer samples." (PMID 31212954, 2019). "The pan-RAR antagonist AGN194310 and the RARγ antagonist AGN205728 were highly effective in driving growth arrest in G1 of cell cycle and death of primary cultures of patients’ prostate cancer cells and the human DU-145, LNCaP, and PC-3 cell line cells (IC50 values of 3.5 to 6 × 10−7 M)." (PMID 36768694, 2023). "Similarly, treatment of the prostate cancer cell lines DU-145, LNCaP, and PC3 with the RARγ agonist AGN205327, or a low level of ATRA to activate just RARγ, stimulated cell growth and colony formation by the cancer stem cell-like cells." (PMID 37569466, 2023). "Patients’ prostate cancer cells appear to have adapted to survive and grow in an abnormally low ATRA environment and may then be reliant on RARγ activation for survival and growth." (PMID 36768694, 2023). "Presently, we do not know how the antagonism of RARγ within, for example, prostate cancer cells effects gene expression." (PMID 36768694, 2023).
prostate carcinoma (continued). "RARγ antagonism, pan-RAR antagonism, and RARγ downregulation led to cell growth which was often followed by cell death for acute myeloid leukaemia, astrocytoma, and cholangiocarcinoma as well as hepatocellular, primitive, neuroectodermal ovarian, and prostate cancer." (PMID 40362593, 2025). "The authors mentioned that these were because RARα, which requires approximately 100-times higher levels of ATRA than RARγ, was not sufficiently activated due to low levels of ATRA in prostate cancer tissues." (PMID 37198667, 2023).
cholangiocarcinoma (14 papers, 2014 to 2026). A carcinoma that arises from the intrahepatic biliary tree (intrahepatic cholangiocarcinoma) or from the junction, or adjacent to the junction, of the right and left hepatic ducts (hilar cholangiocarcinoma). "RARγ over-expression in cholangiocarcinoma is associated with resistance to 5-fluorouracil and a poor prognosis." (PMID 36768694, 2023). "RARγ overexpression in the chemo-resistant bile duct carcinoma cholangiocarcinoma is associated with a poor prognosis and resistance to 5-flurouracil." (PMID 36204679, 2022). "RARγ is oncogenic in acute myeloid leukemia, cholangiocarcinoma, and colorectal, head and neck, hepatocellular, ovarian, pancreatic, prostate, and renal cancers." (PMID 41683719, 2026). "From these findings, the investigators concluded that RARγ plays an oncogenic role in cholangiocarcinoma cells via activation of the Akt/NF-κB and Wnt/β-catenin pathways." (PMID 40362593, 2025). "RARγ overexpression contributed to the multidrug chemoresistance of cholangiocarcinoma cells, which, in part, was related to P glycoprotein upregulation via activation of the Wnt/β-catenin pathway." (PMID 40362593, 2025). "RARγ is an oncogene for many different cancers, including acute myeloid leukaemia and cholangiocarcinoma, and colorectal, head and neck, hepatocellular, ovarian, pancreatic, prostate, and renal cancers." (PMID 40362593, 2025). "Recent findings for the expression of RARγ have revealed an oncogenic role in acute myeloid leukaemia and cholangiocarcinoma and colorectal, head and neck, hepatocellular, ovarian, pancreatic, prostate, and renal cancer." (PMID 40362593, 2025). "The proliferation, migration, invasion, and colony formation ability of cholangiocarcinoma cells in vitro and the tumorigenic potential of cells in nude mice were reduced by the downregulation of RARγ." (PMID 40362593, 2025). "For cholangiocarcinoma, a high level of RARγ expression and a poor prognosis were related to resistance to 5-fluorouracil." (PMID 37569466, 2023). "Si-RNA knockdown of RARγ expression suppressed the xenograft growth of the cholangiocarcinoma cell line QBC939." (PMID 37569466, 2023). "RARγ is also an oncogene for human cholangiocarcinoma, clear cell renal cell carcinoma, colorectal cancer, and pancreatic ductal adenocarcinoma." (PMID 36768694, 2023). "Similarly, overexpression of RARγ in the bile duct carcinoma cholangiocarcinoma (CCA) is associated with a poor prognosis and resistance to 5-fluorouracil." (PMID 35563205, 2022). "For example, RARγ upregulation in cholangiocarcinoma contributes to cancer cell growth and metastasis." (PMID 27756432, 2016). "RARG plays an important role in the proliferation, metastasis, and chemoresistance of cholangiocarcinoma through the simultaneous activation of the Akt/NF-kappaB and Wnt/beta-catenin pathways." (PMID 26526635, 2015). "RARγ was seen to be frequently overexpressed in patients’ cholangiocarcinoma specimens, and high expression was associated with lymph node metastasis." (PMID 40362593, 2025). "Moreover, RARγ is an oncogene regarding overexpression within colorectal, cholangiocarcinoma, hepatocellular, ovarian, pancreatic, and renal cancer cells." (PMID 37569466, 2023). "The findings are complementary regarding disruption to ATRA signaling in cancer cells other than for unknown reasons RARγ is overexpressed by cholangiocarcinoma cells and miR-30a-5p is a tumor promoter." (PMID 37569466, 2023). "Furthermore, induced Wnt/β-catenin signals by several proteins lead to increased ABCB1 expression level and promote drug resistance in different cancer cells such as the PITX2 protein in renal cancer cell lines and retinoic acid receptor gamma in cholangiocarcinoma." (PMID 25401518, 2014). "RARγ is an oncogene for many cancers, including AML, cholangiocarcinoma, colorectal, head and neck, hepatocellular, ovarian, pancreatic, prostate, and renal." (PMID 40362593, 2025).
cholangiocarcinoma (continued). "For the human cholangiocarcinoma cell lines QBC939, SK-ChA-1, and MZ-ChA-1, siRNA knockdown of RARγ expression suppressed cell proliferation, and xenograft tumour growth in nude mice was reduced for stably transfected QBC939 cells." (PMID 36768694, 2023). "The overexpression of RARγ and its activation play roles in the abnormal behaviour of CSCs for a number of cancers that so far include some cases of AML, cholangiocarcinoma, colorectal, clear cell renal cell, hepatocellular, pancreatic ductal adenocarcinoma, prostate, and ovarian." (PMID 36768694, 2023). "Previous studies have shown that overexpressed RARγ could translocate to the cytoplasm in HCC and cholangiocarcinoma." (PMID 28035062, 2017).
colorectal cancer (14 papers, 2016 to 2025). A primary or metastatic malignant neoplasm that affects the colon or rectum. "For colorectal cancer, RARγ overexpression was linked to multidrug resistance with knockdown leading to downregulation of multi-drug resistance 1 and suppression of the Wnt/β-catenin pathway." (PMID 37082619, 2023). "In a three-dimensional tumor spheroid model, immunosuppressive macrophages enhanced the proliferation of HCT116 colorectal cancer cells, which was significantly hindered by RARγ inhibition." (PMID 40807274, 2025). "RARγ overexpression has been reported for good proportions of patients with cholangiocarcinoma, clear cell renal cell carcinoma, colorectal cancer, ovarian cancer, and pancreatic ductal adenocarcinoma." (PMID 37082619, 2023). "Cytosolic RARγ has also been shown to play a role in tumour necrosis factor-induced cell death of HT-29 colorectal cancer cells when the cellular inhibitor of apoptosis (cIAP) activity was blocked." (PMID 36768694, 2023). "RARγ is often over expressed in colorectal carcinoma, and knockdown of RARG within the colorectal carcinoma cell lines HT29, HCT116, RK0 and SW480 enhanced their sensitivity to the chemotherapeutic drugs 5-fluorouracil, oxaliplatin and vincristine sulfate." (PMID 36204679, 2022). "Recently, we reported that RARγ is downregulated in clinical colorectal cancer tissues, and RARγ acts as a tumor suppressor to regulate colorectal tumorigenesis and metastasis by restricting the Hippo-Yap pathway-mediated oncogenic signaling." (PMID 27756432, 2016). "The feasibility of RARγ-targeting approach for cancer therapy is also supported by a recent study showing that RARγ may participate in driving the expression of stemness genes and promote self-renewal of colorectal cancer cells." (PMID 39744424, 2025). "Recent studies have reported that the expression of RARG is decreased in colorectal cancer tissues, suggesting that RARG could be used as a tumor suppressor gene to regulate the metastasis of colorectal cancer by inhibiting the Hippo-YAP signaling pathway." (PMID 36523991, 2022). "Silencing RARγ promotes colorectal cancer cell growth, migration, invasion, and metastasis." (PMID 36175396, 2022). "For example, RARγ functions as a tumor suppressor in colorectal cancer." (PMID 36175396, 2022). "In vitro and in vivo studies showed that silencing RARγ expression enhanced colorectal cancer cell growth significantly, with increased migration, invasion, and metastasis, whereas ectopic expression of RARγ did the opposite, suggesting that RARγ functions as a tumor suppressor in colorectal cancer." (PMID 31590252, 2019). "In colorectal cancer, lactate produced by tumors induces H3K18 lactylation, inhibits retinoic acid receptor gamma (RARγ) transcription in macrophages, increases IL‐6 levels, and enhances tumor‐promoting functions." (PMID 40692663, 2025). "RARγ is overexpressed in the HT29, HCT116, RKO, and SW480 colorectal cancer cell lines as compared to normal HCoEpiC colonic epithelial cells." (PMID 38928275, 2024). "RARγ mRNA and protein were frequently overexpressed in human colorectal cancer tissue as compared to non-tumourous colorectal tissue, and expression was increased in the cell lines HT29, HCT116, RKO and SW480 as compared to the normal colonic epithelial cells HCoEpiC." (PMID 36768694, 2023).
melanoma (10 papers, 2002 to 2025). A malignant, usually aggressive tumor composed of atypical, neoplastic melanocytes. "Previous studies demonstrated that SFT alters the intracellular localization of RARɑ or RARγ in TRCs of HCC or melanoma, respectively, which may be explained by the heterogeneity between different tumor types." (PMID 39605300, 2025). "Additionally, RARα upregulation and RARγ downregulation occur in melanoma." (PMID 33322246, 2020).
acute myeloid leukemia (9 papers, 2019 to 2026). Acute myeloid leukemia (AML) is a group of neoplasms arising from precursor cells committed to the myeloid cell-line differentiation. "In summary, we reported 1 case of acute myeloid leukemia with the NUP98/RARG fusion gene and the RUNX1 mutation that resembled acute promyelocytic leukemia in regards to its morphologic and immunologic features." (PMID 33019444, 2020). "Acute myeloid leukemia with the NUP98/RARG fusion gene and the RUNX1 mutation may be a special subtype of AML and may benefit from the alkaloid-based regimen." (PMID 33019444, 2020). "We report a case of acute myeloid leukemia (AML) with retinoic acid receptor gamma (RARG) rearrangement, exhibiting clinical, morphological, and immunophenotypic features similar to classic acute promyelocytic leukemia (APL)." (PMID 39296977, 2024). "Retinoic acid receptor gamma (RARG) gene rearrangement has been reported in several acute myeloid leukemia (AML) patients." (PMID 36185228, 2022).
acute promyelocytic leukemia (8 papers, 2019 to 2024). An aggressive form of acute myeloid leukemia (AML), characterized by arrest of leukocyte differentiation at the promyelocyte stage, due to a specific chromosomal translocation t(15;17) in myeloid cells. "Over the years, several other types of rare X-RARA fusions have been described, while recently, oncogenic fusion proteins involving other retinoic acid receptors (RARB or RARG) have been associated to very rare cases of acute promyelocytic leukemia." (PMID 32295268, 2020). "RARA rearrangements are well-known to be involved in acute promyelocytic leukemia (APL), but RARG rearrangements can also resemble this kind of leukemia." (PMID 31709264, 2019). "Among the retinoic acid receptors (RARα, RARβ and RARγ), the co-administration of ATRA with arsenic trioxide represents a breakthrough front-line treatment for acute promyelocytic leukemia, acting via modulation of RARα activity, offering new avenues for effectively managing the disease." (PMID 39175546, 2024).
pancreatic cancer (8 papers, 2002 to 2025). "Overexpression of RARγ is common in human pancreatic cancer and predictive of a poor patient prognosis." (PMID 40362593, 2025). "The proliferation of five established patient-derived pancreatic cancer organoids was reduced by the two RARγ antagonists." (PMID 40362593, 2025). "RARγ was required for the proliferation of pancreatic cancer cells because knockout of RARG expression reduced the proliferation of the PANC1, BXPC3, and Sw1990 cell line cells in vitro, with the cells arresting in the S phase of the cell cycle." (PMID 40362593, 2025). "To explore the mechanistic link between MSLN and RARG expression, we utilized a panel of pancreatic cancer cell lines with a range of MSLN levels." (PMID 32616712, 2020). "However, the high RARγ-expression group had a significantly worse prognosis than the low-expression group in pancreatic cancer (median OS 15.7 vs. 24.6 months, p = 0.0011)." (PMID 37198667, 2023). "RARγ-mediated chromatin epigenetic activation was also seen for pancreatic cancer cells." (PMID 37569466, 2023). "To confirm whether RARγ inhibition affects other PDAC cells, we examined the expression of RARγ in various pancreatic cancer cell lines." (PMID 37198667, 2023). "The RARγ antagonists LY2955303 and MM11253 arrested the proliferation of the Panc-1 and PK-1 pancreatic cancer cell lines in the G1 phase of cell cycle without causing apoptosis, and the use of patient-derived organoids confirmed a tumor suppressive effect." (PMID 37569466, 2023). "In addition, our database analyses showed that the expression of RARα was increased in pancreatic cancer, similar to that of RARγ, and that patient prognosis correlated with RARγ expression but not with RARα expression." (PMID 37198667, 2023). "The RARγ antagonists LY2955303 and MM11225 suppressed the proliferation of pancreatic cancer cell lines by inducing G1 arrest, which was not followed by apoptosis." (PMID 40362593, 2025).
leukemia (6 papers, 2007 to 2024). A malignant (clonal) hematologic disorder, involving hematopoietic stem cells and characterized by the presence of primitive or atypical myeloid or lymphoid cells in the bone marrow and the blood. "The regulation of the subcellular content of CDK1 and RARγ by all-trans retinoic acid is an important process for achieving an effective response in treatment of leukemia." (PMID 32596342, 2020). "They analyzed the prognostic impact of APL with alternative RARA or RARG fusions, showing that the 3-year overall survival (OS) and leukemia-free survival (LFS) of APL with alternative RARA or RARG were worse than that of PML-RARA cohort." (PMID 31207999, 2019). "Despite the fact that clinical feature of RARG-rearranged leukemia is similar to APL, its treatment is totally different." (PMID 31207999, 2019). "RARG rearranged leukemia is a rare specific subtype of AML, but its characterization is very ambiguous because its features are so strongly similar to APL." (PMID 31709264, 2019). "Some researchers supposed that APL-like leukemia might bear genetic mutation of other members of retinoic acid receptors (RARs), such as RARB or RARG." (PMID 34884990, 2021). "As some studies have shown, RARα and RARγ may be involved in apoptosis induction in immortalized keratinocytes and leukemia cells." (PMID 18166136, 2007).
acne (5 papers, 2021 to 2024). An inflammatory process of the sebaceous glands which is characterized by comedones, nodules, papules and/or pustules on the skin. "Recent in vitro and in vivo studies of RARγ have revealed the potential use of agonists and antagonists to treat diseases as diverse as cancer, heterotopic ossification, psoriasis, and acne." (PMID 38928275, 2024). "Unlike earlier retinoids, trifarotene specifically targets the retinoic acid receptor gamma (RARγ), offering more precise modulation of acne-related processes like follicular differentiation and inflammation." (PMID 39518974, 2024). "Trifarotene (CD5789) is a recently synthesized RARg selective agonist that has been approved for the treatment of acne." (PMID 35796328, 2023). "Background and Objectives: Trifarotene is a topical retinoid selective for retinoic acid receptor gamma that was recently approved for treatment of acne vulgaris." (PMID 34746181, 2021). "Highly selective agonists and antagonists of RARγ are available and studies to date have revealed that they have considerable potential as therapeutics for diseases as diverse as cancer, psoriasis, heterotopic ossification, and acne." (PMID 38928275, 2024). "The structure of the RARγ agonist CD437 and its binding to the receptor in the ligand binding pocket was used to design a drug candidate for treating acne." (PMID 38928275, 2024).